CD163 (CD163 molecule)
Diseases named in the same sentence as CD163 in open-access papers (continued):
Sharing a sentence is not in itself a finding about the gene and the disease.
breast carcinoma (continued). "Interestingly, although high DEK/CD163 dual expression did not correlate with RFS in basal subtype or HER2+ breast cancer, there was a strong correlation with decreased RFS in luminal A subtype and a similar correlation with luminal B subtype (data not shown)." (PMID 32708944, 2020). "However, for the expression of CD163 in the tumor tissues (CD163Tissue), only 17 (15.7%) cases of breast cancer and no (0%) cases of benign breast disease showed high expression." (PMID 33178603, 2020). "Furthermore, we observed a strong positive correlation between the expression of DEK and the M2 TAM marker CD163 (p = 0.005, data not shown) in primary breast cancers." (PMID 32708944, 2020). "Furthermore, we performed a retrospective study and systematic review of the published studies on CD68- and CD163-positive macrophages in non-metastatic breast cancer." (PMID 31528210, 2019). "In addition, breast cancer and sepsis HLA-DRlow/- monocytes, when compared to HLA-DR++ monocytes, displayed significantly reduced levels of the co-receptors CD86, CD80 and the suggested anti-inflammatory monocyte-macrophage marker CD163." (PMID 25992611, 2015). "Positivity of macrophages only for CD163 has been found to be associated with tumor stage and lymph node status, whereas macrophage positivity for only CD68 has been associated with the molecular subtype of breast cancer, independent of other clinicopathological parameters." (PMID 41256322, 2025). "This suggests that the pro-tumoral functions of CD163+ TAMs in HER2+ breast cancer are not obstructed by trastuzumab or that CD163+ TAMs might even suppress its actions, even though patients with a high CD163+ TAM count also benefitted from the adjuvant trastuzumab therapy." (PMID 38339385, 2024). "Expression of CD163, HER-2 and microcalcifications was not independent prognostic factors for breast cancer (P = 0.078, 0.064 and 0.747 respectively)." (PMID 34983451, 2022). "Furthermore, the hypoxia and acidosis commonly associated with CAIX expression, and the immune modulation associated with these features, may be critical factors driving the prognostic dichotomization of G-CSFhigh and CD163+ M2 macrophage-infiltrated non-luminal breast cancers." (PMID 33804486, 2021). "Flow cytometric analysis revealed the levels of M2 macrophage marker (CD206, CD163) and M1 macrophage marker (HLA-DR) were very low in MCF-7 cells culture alone, suggested no expression of macrophage marker in breast cancer cells." (PMID 27387344, 2016). "Taken together, infiltration of CD163+ and CD68+ macrophages into TS, but not TN, is of clinical relevance for breast cancer patients and highlights the importance of analyzing the localization rather than merely the presence of TAMs as a prognostic marker." (PMID 22824040, 2012). "Therefore, the aim of this study was to analyze whether CD163 can be used as a marker for TAMs and to compare its prognostic value with the more frequently used pan-macrophage marker CD68 in a tissue microarray (TMA) with tumors from 144 breast cancer patients." (PMID 22824040, 2012). "Here we show that infiltration of CD163+ and CD68+ macrophages into TS, but not TN, is of clinical relevance for breast cancer patients." (PMID 22824040, 2012). "Studies comparing CD163 and CD206 TAMs in breast cancer are lacking." (PMID 38893266, 2024). "The pathological study indicated that increased density of CD204+ TAMs was closely associated with cancer cell proliferation and worse clinical course in breast cancer, and the density of CD204+ TAMs was a significant prognostic factor rather than the density of CD68+ or CD163+ TAMs." (PMID 39199574, 2024). "Here, we report the 10-year OS, breast cancer-specific survival (BCSS) and disease-free survival (DFS) rates according to the number of M2 TAMs (CD163+) and all TAMs (CD68+) in a cohort of 278 non-metastatic breast cancer patients, every second of which was HER2+ (n = 139)." (PMID 38339385, 2024).
breast carcinoma (continued). "Moreover, high levels of the M2 macrophage marker CD163, but not CD204 significantly correlated with a shorter survival time in patients with breast cancer." (PMID 37551997, 2023). "This meta-analysis further supports the clinical significance of TAMs in breast cancer, and both CD68- and CD163-positive TAMs could be prognostic markers in non-metastatic breast cancer." (PMID 31528210, 2019). "The expression of three of these genes (CD163, CXCR4, THBS1) was found to predict relapse-free survival in a large, publically-available transcriptomic dataset generated from the tumors of patients with TNBC, but not other breast cancer subtypes." (PMID 30254632, 2018). "To determine whether macrophages cells do not contaminate the isolated cells prepared from breast cancer tissues, we used immunofluorescence to investigate the expression of various macrophage surface markers including F4/80, CD68 and CD163." (PMID 28178651, 2017). "CD8+ and CD163+ cells were quantified by immunohistochemistry of formalin-fixed, paraffin-embedded (FFPE) tumor tissue samples from a cohort totaling 162 patients with histologically-confirmed primary invasive non-metastatic ductal breast cancer diagnosed between 2000 and 2015." (PMID 28428887, 2017).
glioma (139 papers, 2009 to 2026). A benign or malignant brain and spinal cord tumor that arises from glial cells (astrocytes, oligodendrocytes, ependymal cells). "Loss of CD163 expression inhibited both cell cycle progression and proliferation of glioma cell lines and primary glioma cells." (PMID 39941886, 2025). "CD68 (pan‐macrophage/microglia) and CD163 (M2‐associated) have been linked to worse outcomes in glioma and are widely used surrogates of TAM burden/polarization." (PMID 41354084, 2025). "Accumulating evidence has proven the immune system has an essential role in malignancy pathogenesis, and LGALS3 is closely correlated with CD163+ tumor-associated macrophages (TAM) in glioma." (PMID 38643145, 2024). "Increased CD163 staining on IHC was found to be an independent prognostic factor for patients with glioma and associated with increased risk of recurrence on both univariate and multivariate analyses." (PMID 39409905, 2024). "We detected several subtypes of infiltrating lymphocytes, as well as CD163- and CD11b-positive cells, highly suggestive of the presence of TAMs inside the glioma-associated microenvironment." (PMID 36358353, 2022). "This analysis also revealed a correlation between tumor CD73 and myeloid CD11b and CD163, suggesting that similar populations of microglia associate with tumor cells in pediatric and adult gliomas." (PMID 35973991, 2022). "Regarding brain tumour-related studies, investigation with clinical glioma samples have found an association between high CD163+ cells (M2 marker) and glioma progression." (PMID 34071393, 2021). "In particular, VAP-1/CD163 coexpression showed excellent diagnostic accuracy in gliomas (AUC = 0.8008)." (PMID 32349342, 2020). "We demonstrated that high VAP-1 expression levels positively correlated with CD163+ M2 activation and coexpression of these two proteins was associated with worse survival in gliomas (p < 0.0001)." (PMID 32349342, 2020). "In gliomas, the analysis of GAMs revealed a predominant population of CD163+ and CD204+ anti-inflammatory M2 GAMs in association with higher tumor grade and a worse patient survival." (PMID 29389898, 2018). "CD163-positive macrophages have been associated with a number of malignancies, including glioma." (PMID 40191733, 2025). "Microglia recruited by glioma are reported to acquire M2-like or mixed M1/M2-like phenotypes, thus the expression of anti-inflammatory markers CD163 and TREM2 by large proportions of PA-associated microglia supports the idea that these represent recruited microglia." (PMID 39948623, 2025). "However, one study showed that an increased number of CD163-positive glioma-associated microglia/macrophages in the tumor core was related to better survival." (PMID 36551651, 2022). "Furthermore, VAP-1/CD163 coexpression exhibited excellent diagnostic accuracy in gliomas (AUC = 0.8008)." (PMID 32349342, 2020). "LGALS3 was an independent poor prognostic marker in diffusely infiltrating gliomas and was positively correlated with immune cell infiltration, particularly CD163+ tumor-associated macrophages in the TCGA dataset, Rembrandt dataset, and our SYSUCC cohort (R = 0.419, 0.627, and 0.724)." (PMID 32528967, 2020). "Immunofluorescence analysis confirmed upregulation of ASM protein in high-grade, IDH-wildtype gliomas, with a strong positive correlation with CD163 expression in clinical samples." (PMID 41795144, 2026). "Treatment with an anti-programmed death-ligand 1 (PD-L1) antibody has demonstrated a significant reduction of CD163+ macrophage infiltration in glioma, implying a potential relationship between CD163 expression and immune checkpoint mechanisms." (PMID 40361384, 2025). "CD163 is considered a potential therapeutic target for macrophage-directed therapy in cancers such as glioma and gastric cancer." (PMID 39975548, 2025).
glioma (continued). "Microglia/macrophages, which express Iba1 and CD163 markers, likely play a significant role in shaping the tumor microenvironment and contributing to glioma development." (PMID 40361384, 2025). "The secretion of IL-6, facilitated by hypoxic glioma-derived exosomes, has an additive effect on increasing CD163 and IL-10 expression via the same STAT3 pathway, thereby enhancing tumor progression." (PMID 40361384, 2025). "Overall, the expression of CD163 on microglia/macrophages appears more common in high-grade glioma tissue." (PMID 40361384, 2025). "As shown in various studies, CD163 expression was correlated with worse prognosis of various kind of cancer, including glioma and colorectal cancer." (PMID 41498045, 2025). "Iba1 and CD163 appear to have both unique and shared roles in glioma pathobiology, and both have the potential to be targeted through different molecular and cellular mechanisms." (PMID 40361384, 2025). "By studying the regulation of Iba1 and CD163, we aim to better understand the role of TAMs in gliomas." (PMID 40361384, 2025). "Iba1+ and CD16+ cells prevail in human low-grade gliomas, whereas CD68+ and CD163+ cells increase in high-grade gliomas, with a significant correlation between patients’ worsening overall survival." (PMID 38671983, 2024). "Consistent with our in vitro results, the depletion of CEBPB in transplanted glioma cells not only significantly reduced the overall TAMs (Iba1 positive) content but also markedly decreased the content of CD206 or CD163 positive M2 TAMs." (PMID 38994023, 2024). "Linear regression analysis revealed that the number of CD68‐positive cells was significantly positively correlated with the number of GFAP+PDPN+ cells in glioma, with CD68+CD163+ cells showing a similar association with GFAP+PDPN+ cells." (PMID 38470096, 2024). "Multiplexed fluorescence immunohistochemistry staining of PDPN, GFAP, CD68, and CD163 were performed in glioma tissue microarray." (PMID 38470096, 2024). "Our findings demonstrated that PDPN is notably correlated with the expression of CD68 and CD163 in glioma tissues." (PMID 38470096, 2024). "CD163 is normally expressed in glioblastoma stem cells and regulates the proliferation and self-renewal of glioma by impacting the CD163/AKT/GSK3β/β-catenin pathway." (PMID 39457052, 2024). "Immunofluorescence staining revealed a significant increase in CD163+ microglia in the archetypal IDH glioma." (PMID 37166058, 2023). "The results revealed that compared with low-grade gliomas, the intensity of CD163 protein in high-grade gliomas was also enhanced (P < 0.05), and there was a good match between ISG20 and CD163 expression in the serial sections." (PMID 37380984, 2023). "We also examined RPN1, GYS1, and CD163 (M2 macrophage marker) expression levels in 83 glioma tissues." (PMID 38022537, 2023). "Glioma tissues with increased GYS1 or RPN1 expression also exhibited elevated CD163 expression, aligning with our pan-cancer analysis findings." (PMID 38022537, 2023). "Immunofluorescence assay was performed to further explore the cellular localization of ISG20 and CD163 in glioma samples." (PMID 37380984, 2023). "CD163, a membrane protein considered as the most specific M2 macrophage phenotypic marker, predicts poor prognosis in patients with glioma." (PMID 37009153, 2023). "A previous study has revealed that increased CD163+ macrophages not only enhanced cancer stemness but also correlated with TMZ resistance in gliomas." (PMID 35845613, 2022). "CD163 is a classic and distinctive biomarker for macrophage infiltration and is involved in glioma progression and poor survival." (PMID 36119086, 2022). "The result showed CD163 expression was higher in high-grade gliomas (Grade 3 and 4) in comparison to low-grade gliomas (Grade 2)." (PMID 35673564, 2022). "An increase in CD163 expression is similarly reported in other high-grade canine tumors, such as lymphomas and gliomas." (PMID 35937296, 2022).
glioma (continued). "Bioinformatic prediction and IHC analysis revealed that GMFG expression obviously correlated with the macrophage marker CD163 in gliomas." (PMID 35845613, 2022). "CD68+p-STAT3+ (P = 0.0306) and CD163+p-STAT3+ (P = 0.0165) cells were significantly enriched in regions of necrosis in gliomas and brain metastases, respectively." (PMID 35316217, 2022). "More importantly, we further manifested that the number of CD163+ CD101+ cells was significantly abundant in the grade 4 glioma compared to that in grade 2 and grade 3 gliomas." (PMID 35350788, 2022). "CD163 expression induces Stat3 activation, and direct contact between macrophages and glioma cells induces strong CD163 expression in macrophages via Stat3 activation." (PMID 35132816, 2022). "Intratumoral CD68+ (P = 0.0029), CD11c+CD68+ (P = 0.0018) and CD11c+CD68+CD163+ (P = 0.0029) cells were more likely to express p-STAT3 in gliomas." (PMID 35316217, 2022). "The populations of CD163+ M2 macrophages have been shown to be enriched in high-grade gliomas, and their performance is inversely related to patient survival." (PMID 35570844, 2022). "As our previous findings, CD163+ M2 infiltration in glioma tissues was progressively correlated with tumor malignancy and worse outcome." (PMID 35570844, 2022). "To further validate our findings, we performed IHC staining for one of the TAMs markers (CD163) and found that GMFG expression was significantly associated with CD163 expression in gliomas." (PMID 35845613, 2022). "It was showed that CD163 expressed highly in CD133-positive glioma stem cells, and contributed to gliomagenesis." (PMID 34345203, 2021). "Further analysis revealed that glioma tissues with high GSDMD expression had abundant macrophage cell (CD68+/CD163+ double positive) infiltration by using IF staining." (PMID 34830775, 2021). "These were consistent with a previous result, which found that CD163 predicts poor prognosis in glioma patients." (PMID 34395626, 2021). "By measuring the expression of CD163, the infiltration degree of M2 macrophage in glioma can be determined." (PMID 32509446, 2020). "High gene expression ratio of CD163/CCL3 in gliomas, as M2 and M1 macrophage markers, respectively, and PD-1+ CD4 T cells in the blood of tumor patients were associated with poor prognosis." (PMID 33050070, 2020). "Meanwhile CD163 regulates the stemness of glioma, anti-PD-L1 antibody treatment significantly reduced infiltration of CD163+ macrophage in glioma." (PMID 33408717, 2020). "We found that CD163+ TAMs were abundant in glioma, particularly in GBM and that LGALS3 was strongly correlated with the number of TAMs." (PMID 32528967, 2020). "This study demonstrated that inhibition of miR-454-3p in glioma cells promoted M2 macrophage polarization, corresponding to elevated expression of II1b, Cd86, and Nos2, and reduced expression of Cd163, Ym1 and Mrc1 in macrophages." (PMID 33363140, 2020). "In particular, MG (Iba1+ CD163−) were diffusely scattered throughout gliomas, while Iba1+CD163+ BMDMs and CD206+, CD169+, and CD209+ subsets of BMDMs were found in close proximity to blood vessels in gliomas." (PMID 33374253, 2020). "A previous study confirmed that CD163+ TAMs played an important role in the biological process of glioma and that high expression of CD163 predicted poor prognosis in glioma patients." (PMID 32528967, 2020). "Most importantly, we found that LGALS3 was involved in the regulation of the glioma immune microenvironment, particularly CD163+ TAMs." (PMID 32528967, 2020). "In conclusion, VAP-1 and TAM CD163 M2 coexpression was found in glioma tissues belonging to a highly malignant subgroup that was associated with poor prognosis." (PMID 32349342, 2020). "High CD163 levels have recently been suggested to be a potential biomarker for poor prognosis in a number of solid tumours, including gliomas, oestrogen-receptor-positive breast cancer and head and neck squamous cell carcinomas." (PMID 32070062, 2020).